ENSG00000222043 (novel transcript)
Gene: Long non-coding RNA gene on chromosome 2 (177,264,359 to 177,265,515, forward strand). Ensembl gene ENSG00000222043.
Gene Ontology:
Molecular function: ribosome binding